ANXA2 (annexin A2)
Diseases named in the same sentence as ANXA2 in open-access papers (continued):
Sharing a sentence is not in itself a finding about the gene and the disease.
esophageal squamous cell carcinoma (8 papers, 2013 to 2025). Esophageal squamous cell carcinoma (ESCC) is a type of esophageal carcinoma (EC) that can affect any part of the esophagus, but is usually located in the upper or middle third. "Loss of FBXW7 promotes esophageal squamous cell carcinoma (ESCC) progression by enhancing ANXA2 to activate the MAPK pathway." (PMID 38688909, 2024). "Conversely, K48/K11-linked ubiquitin chains assembled by FBXW7 or TRIM65 target ANXA2 for 26S proteasomal degradation, leading to protein loss in FBXW7-deficient esophageal squamous cell carcinoma and conferring chemoresistance by upregulating MAPK signaling." (PMID 41185558, 2025). "There have been only a few studies of ANXA2 in esophageal tumors, which present a complex picture with seemingly contradictory findings regarding its role in esophageal squamous cell carcinoma (ESCC)." (PMID 39594718, 2024). "We previously found that ANXA2 is upregulated in esophageal squamous cell carcinoma (ESCC)." (PMID 30081903, 2018). "In this study, we provided evidence that ANXA2 promotes the progression of esophageal squamous cell carcinoma (ESCC) through the downstream target threonine tyrosine kinase (TTK)." (PMID 38658569, 2024).
neuroblastoma (8 papers, 2017 to 2025). Neuroblastoma (NB) is the most common solid, extracranial childhood tumor. "In pediatric neuroblastoma, AnxA2 depletion attenuated NFκB activity and enhanced anticancer drug sensitivity, which improved chemotherapy in a xenograft model for neuroblastoma." (PMID 33810523, 2021). "To further demonstrate the effect of ANXA2 on drug sensitivity in vivo, we generated a subcutaneous xenograft neuroblastoma model." (PMID 28814318, 2017). "Two studies investigated the expression of annexin A2 in neuroblastoma." (PMID 40426729, 2025). "Moreover, Anxa2 knockdown reduces the transcriptional activity of NF-κB and downregulates nuclear translocation of p50 in the neuroblastoma cell line." (PMID 38253182, 2024). "STRING database analysis predicted that ANXA2 binds to STAT3, and thus, we speculate that STAT3 may be involved in the downstream signalling pathway of Nectin2 and ANXA2 during neuroblastoma pathogenesis." (PMID 36916296, 2023). "It has been observed that the ionomycin treatment of murine neuroblastoma cells results in translocation to the cell membrane of ANX, in the following order: ANXA2, ANXA4, ANXA6, ANXA1, ANXA5." (PMID 35207075, 2022).
osteoporosis (8 papers, 2012 to 2023). A condition of reduced bone mass, with decreased cortical thickness and a decrease in the number and size of the trabeculae of cancellous bone (but normal chemical composition), resulting in increased fracture incidence. "ANXA2 is an important osteoporosis susceptibility gene, which is involved in osteoporosis in humans." (PMID 23620822, 2013). "We found that the expression of AnxA2, AnxA5 and AnxA6 was distributed along the edge of cancellous bone where the osteoblasts were distributed, and their expression was lower in the osteoporosis group than in the sham group." (PMID 37940665, 2023). "The expression levels of ANXA2 were elevated in the osteoporosis mice model mice but were inhibited in osteoporosis model mice with the over-expression of miR-425-5p." (PMID 34879879, 2021). "The expression levels of ANXA2 were elevated in the osteoporosis model mice at both mRNA and protein levels (P < 0.01), while reduced in osteoporosis model mice transfected with miR-425-5p mimics (P < 0.01)." (PMID 34879879, 2021). "For instance, annexin A2 (Anxa2) is a phospholipid-binding protein that is over-expressed in some tumors and in the blood of people with osteoporosis." (PMID 29447215, 2018). "In conclusion, miR-425-5p could modulate osteoporosis by targeting ANXA2 both in vitro and in vivo." (PMID 34879879, 2021). "Studies have found that the ANXA2 gene is involved in the pathogenesis of osteoporosis, but its mechanism in MSC differentiation has not been reported." (PMID 34879879, 2021).
pulmonary fibrosis (8 papers, 2015 to 2025). Chronic progressive interstitial lung disorder characterized by the replacement of the lung tissue by connective tissue, leading to progressive dyspnea, respiratory failure, or right heart failure. "Annexin A2 is a specific BLM target to induce pulmonary fibrosis by impeding TFEB-mediated autophagic flux." (PMID 36386240, 2022). "In the research, it is further proved that Glu139 (E139) of ANXA2 (ANXA2E139A) is required in bleomycin reduced pulmonary fibrosis." (PMID 33995636, 2021). "ANXA2 was identified a bleomycin binding site in the pulmonary fibrosis which result in resistance for bleomycin treatment." (PMID 33995636, 2021). "In a BLM mouse model of pulmonary fibrosis, BLM binding with ANXA2 impedes transcription factor EB (TFEB)-induced autophagic flux; the inhibition of profibrotic cytokines induces autophagy flux and decreases the production of collagen to alleviate pulmonary fibrosis." (PMID 33671452, 2021). "We speculate that, under normal conditions, AnxA2 is involved in physiological COL1A2 regulation to prevent excessive deposition of type I collagen which is characteristic of many fibrotic disorders such as systemic sclerosis, hepatic cirrhosis and pulmonary fibrosis [Varga and Jimenez, 1995]." (PMID 25290763, 2015).
adenomyosis (7 papers, 2015 to 2022). The growth of endometrial tissue inside the muscular wall of the uterine corpus. "The preoperative serum level of ANXA2 was measured by enzyme-linked immunosorbent assay in 30 patients with adenomyosis and 15 patients with hysteromyoma." (PMID 31183557, 2019). "In this study, the expression of ANXA2 was detected by immunohistochemical S-P method, followed by the Pearson correlations for the correlation analysis of ANXA2 with adenomyosis-associated dysmenorrhea." (PMID 31183557, 2019). "Closer to endometriosis, ANXA2 has been implied in adenomyosis-associated dysmenorrhea." (PMID 32106990, 2020). "However, little is known about the relationship between ANXA2 and adenomyosis-associated dysmenorrhea." (PMID 31183557, 2019). "These molecules (ANXA2) can play a dual role in the pathogenesis of adenomyosis: first, through spreading potential and, second, through angiogenic capacity." (PMID 35206475, 2022). "SPP1, LIF, TCN1 and CLDN4 were common to adenomyosis and healthy groups of genes, while ANXA2, EDNR8, MMP26, DEPP1, ABCC3, CDA and SLC1A1 were common to endometriosis and healthy groups." (PMID 32933042, 2020). "Meanwhile, the levels of preoperative serum ANXA2 of patients with adenomyosis (n = 30) and uterine myoma (n = 15) were also measured by enzyme-linked immunosorbent assay (ELISA)." (PMID 31183557, 2019). "The expression of ANXA2 was detected by immunohistochemical S-P method in ectopic and eutopic endometrium tissues from 30 patients with adenomyosis who underwent hysterectomy." (PMID 31183557, 2019). "Serum level of ANXA2 in adenomyosis group was significant higher than that in control group (P < 0.01)." (PMID 31183557, 2019). "The preoperative serum level of ANXA2 was markedly higher in patients with adenomyosis compared with the patients with hysteromyoma (P < 0.05)." (PMID 31183557, 2019). "The increased ANXA2 may contribute to the occurrence and development of adenomyosis, and may play a important role in the dysmenorrhea." (PMID 31183557, 2019). "The study showed that a group of estrogen-responsive proteins were significantly altered and amongst them, Annexin 2 (ANXA2) was identified as a key player in adenomyosis development by inducing both metastasis and proangiogenesis of adenomyotic endometrial cells." (PMID 30388215, 2019). "Additionally, evidence-based data unraveled an active role for ANXA2 in the pathogenesis of adenomyosis through conferring the ability of endometrial carcinomas to metastasize and proangiogenic capacity." (PMID 31183557, 2019). "At the same time, the increased expression of ANXA2 may promote the angiogenesis activity of adenomyosis endometrial cells through the HIF-1 alpha /VEGF-A pathway." (PMID 26362938, 2015). "Currently, the studies investigating ANXA2 in endometrial tissues are limited, with only a few studies showing that ANXA2 might play an important role in endometriosis, adenomyosis angiogenesis, and embryo implantation." (PMID 26362938, 2015). "Upregulated Anxa2 expression is correlated with the expression of EMT markers in human adenomyosis." (PMID 26307676, 2015). "The invasive and metastatic potential involved in adenomyosis was achieved by ANXA2-induced β-catenin/T-cell factor associated EMT-like switch in endometrial cells, and the proangiogenic capacity in local lesion was enhanced via ANXA2/HIF-1α/VEGF-A pathway activation." (PMID 30388215, 2019). "In the ectopic endometrium, but not in the eutopic endometrium, of women with adenomyosis, ANXA2 expression was positively correlated with the severity of dysmenorrhea (R = 0.831, P = 0.000)." (PMID 31183557, 2019). "Several studies revealed that Anxa2 is involved in EMT in avian heart development and adenomyosis." (PMID 26307676, 2015).
Alzheimer disease (7 papers, 2021 to 2025). A progressive, neurodegenerative disease characterized by loss of function and death of nerve cells in several areas of the brain leading to loss of cognitive function such as memory and language. "Notably, many of these genes have been well-studied in Alzheimer’s disease, while others, such as the AnxA2 gene, a hub gene recently reported to be associated with AD in the hippocampus, remain poorly understood regarding their role in AD." (PMID 39456526, 2024). "Relevant for diseases associated with the accumulation of aggregated proteins, ANXA2 expression is enhanced at the cell periphery in reactive astrocytes positioned in close proximity to senile plaques and degenerating neurons of Alzheimer’s disease human post mortem brains." (PMID 33629273, 2021). "Although reports on the dysfunction of annexin A2 appear primarily in the field of cancer research, a role for this protein in diseases of the nervous system, such as Alzheimer’s disease and Niemann–Pick type C disease, has also been demonstrated." (PMID 35629417, 2022). "For instance, in tauopathies, and in particular Alzheimer’s disease, ANXA2 may participate in amyloid protein degradation, cellular antioxidant defense, and anti-inflammatory processes." (PMID 40141747, 2025). "Furthermore, it has been demonstrated that, in conjunction with annexin A2, annexin A6 interacts with tau, which is thought to contribute to the pathological redistribution of tau in Alzheimer’s disease." (PMID 37108598, 2023). "However, aided by deep sequencing data, various SNPs were identified, suggesting a potential involvement of AnxA1 in Alzheimer’s disease, and revealed roles for AnxA2 in sickle cell disease, but also cardiovascular risk due to elevated LDL cholesterol." (PMID 33810523, 2021).
autoimmune disease (7 papers, 2017 to 2025). A disorder resulting from loss of function or tissue destruction of an organ or multiple organs, arising from humoral or cellular immune responses of the individual to their own tissue constituents. "Taken together, these results revealed a crucial role of ANXA2 in a variety of autoimmune diseases, such as autoimmune uveitis, SLE, and IBD, via the activation of inflammatory signaling pathways." (PMID 37828081, 2023). "Regarding Annexin A2, Researchers have primarily focused on autoimmune diseases and the interaction between nidoviruses and Annexin A2 to develop broad-range antiviral agents." (PMID 37482693, 2023). "ANXA2 may play a role in a number of non-neoplastic conditions, such as autoimmune diseases, thrombosis, hemorrhagic disorders and viral infections." (PMID 36713082, 2023).
endometriosis (7 papers, 2015 to 2026). The growth of functional endometrial tissue in anatomic sites outside the uterine body. "Our study also suggested that the level of ANXA2 in ectopic endometrial tissues was markedly downregulated compared with normal endometrial tissues, and inhibited ANXA2 expression was correlated with the enhanced malignant-like phenotype of endometriosis." (PMID 34055578, 2021). "ANXA2 also serves as an important player between retrograded endometrial tissues and immune suppression during the pathology of endometriosis." (PMID 34055578, 2021). "To define the roles of miR-342/ANXA2 axis in the occurrence of endometriosis, we co-transfected endometrial stromal cells with NC mimic + NC vector, miR-342 mimic + NC vector, NC mimic + ANXA2 vector, or miR-342 mimic + ANXA2 vector, respectively." (PMID 34055578, 2021). "ANXA2 is contained by endometriosis-specific exosomes in peritoneal fluid of endometriosis patients." (PMID 34055578, 2021). "ANXA2 has also been proposed to be expressed at a low level in peritoneal macrophages isolated from women with endometriosis." (PMID 34055578, 2021). "An earlier proteomics study showed ANXA2 dysregulation within the eutopic endometrium of endometriosis patients." (PMID 32106990, 2020). "It was observed that ANXA2 significantly increased the expression of Cyclooxygenase 2 in peritoneal macrophages of patients with endometriosis by PCR and Western-blot methods." (PMID 31183557, 2019). "Taken together, miR-342 targets and negatively mediates the ANXA2 expression in endometriosis." (PMID 34055578, 2021). "We first characterized the levels of miR-342 and ANXA2 in 31 cases of normal endometrium from patients with grade II-III cervical intraepithelial neoplasia or patients with hysterectomy versus ectopic endometrial tissues of 42 patients with endometriosis." (PMID 34055578, 2021). "Thus, PRDX1 and ANXA2 are linked to placental/fetal development, while ITIH4 most likely derives from inflammatory monocytes prevalent in endometriosis." (PMID 32106990, 2020). "Five proteins were found exclusively in the endometriosis groups: PRDX1, H2A type 2-C, ANXA2, ITIH4, and the tubulin α-chain." (PMID 32106990, 2020). "Taken together, miR-342 targets ANXA2 to activate the PI3K/AKT/mTOR signaling pathway, thereby promoting the malignant-like phenotype of endometrial stromal cells, highlighting miR-342 inhibition as a promising approach for the treatment of endometriosis." (PMID 34055578, 2021). "Moreover, cyto-hub gene analysis revealed that CSNK2A1, CSNK2A2, TOP1, PRKACA, RBM39 (plasma), ALB, ACTB, GAPDH, FN1, APOA1 (serum), S100-A9, CXCL1, IL1RN, CSTA, S100-A8 (menstrual blood) and THBS1, ALB, CD44, ANXA2, and LUM (urine) were the top 5 proteins expressed in women with endometriosis." (PMID 39061077, 2024).
lupus nephritis (7 papers, 2012 to 2026). Glomerulonephritis in the context of systemic lupus erythematosus. "Expression of ANXA2 was also significantly increased in the tubulointerstitium of patients with lupus nephritis (5.401 versus 4.521, p = 0.0002) and FSGS (6.845 versus 5.930, p = 0.0502) compared to healthy controls." (PMID 40889685, 2025). "Cluster 5 expressed Anxa2, whose expression correlated with development of lupus nephritis and kidney inflammation." (PMID 41213970, 2025). "AnxA2 is also the target of autoantibodies in several diseases affecting the kidneys, including anti-phospholipid antibody syndrome, lupus nephritis, and idiopathic nephrotic syndrome." (PMID 40889685, 2025). "High circulating levels of anti-ANXA1 and anti-ANXA2 antibodies characterize lupus nephritis implying a reduced anti-inflammatory effect." (PMID 37176025, 2023). "Additionally, Annexin A2 (ANXA2) is associated with organ-targeted injury, such as lupus nephritis (LN) in systemic lupus erythematosus (SLE), through its interactions with anti-double-stranded DNA antibodies (anti-dsDNA)." (PMID 41542857, 2026).
pancreatic adenocarcinoma (7 papers, 2011 to 2023). "Annexin A2 (ANXA2) encodes an oncoprotein whose expression has been found to correlate with poorer overall survival (OS) of pancreatic adenocarcinoma (PAAD) patients." (PMID 36453020, 2023). "Moreover, Anxa2 plays a crucial role in the tumorigenesis and progression of pancreatic adenocarcinoma." (PMID 33817317, 2021). "Dual luciferase reporter assays confirmed that KRAS and ANXA2 can bind miR-206 directly at the “seed site”, which is consistent with previous reports showing that miR-206 targets KRAS and ANXA2 in pancreatic adenocarcinoma." (PMID 27191262, 2016). "ANXA2 overexpressed in colon adenocarcinoma (COAD), rectum adenocarcinoma (READ), liver hepatocellular carcinoma (LIHC), pancreatic adenocarcinoma (PAAD), stomach adenocarcinoma (STAD)." (PMID 33995636, 2021).
steatosis (7 papers, 2019 to 2025). Increased lipid within the cytoplasm of cells. "We also analyzed the expression levels of Trem2, Anxa2, Ttc39a, and Gdf15 across various stages of the disease, including steatosis, NASH, and fibrosis." (PMID 39697329, 2024). "The consistent upregulation of Trem2, Anxa2, Ttc39a, and Gdf15 across all stages of liver disease—from steatosis and NASH to fibrosis—suggests that these genes play a pivotal role in the progression of NAFLD." (PMID 39697329, 2024). "Sobolewski et al36 reported that S100A11/ANXA2 belongs to a tumor oncogene/tumor suppressor gene network, which can be deregulated through steatosis at an early stage, thereby participating in the development of inflammation and HCC." (PMID 39128058, 2024). "ANXA2 is also involved in the regulation of lipid content in liver cells; it is one of the most important markers of steatosis." (PMID 37004042, 2023). "Additionally, TLR4 activates downstream NF-κB and c-Jun transcription factors, which enter the nucleus and bind to the promoter region of ANXA2, reducing autophagy by promoting ANXA2 expression, leading to steatosis." (PMID 39683601, 2024). "We then investigated whether FFA-induced steatosis would play a role in ANXA2 expression." (PMID 39273539, 2024). "In addition, ANXA2 depletion can attenuate diet-induced steatosis and liver injury in mice." (PMID 39273539, 2024). "To further investigate the effect of FFA-induced steatosis on KRT17 and ANXA2 expression, we assessed both the transcriptional and protein levels." (PMID 39273539, 2024). "Precious analysis revealed that ANXA2, PRKCE, and OXT are three important genes that are involved in steatosis stage of NAFLD." (PMID 31191837, 2019). "Deregulation of ANXA2, PRKCE, and OXT is a critical event in steatosis." (PMID 31191837, 2019). "However, role of ANXA2 in NAFLD is reported previously, here it is introduced as the top related gene in NAFLD (especially steatosis stage)." (PMID 31191837, 2019). "In our study, FFA-induced steatosis upregulated the expression of ANXA2 mRNA and cytoplasmic protein levels in HepG2 cells treated with oleic and palmitic acids; however, it did not affect the nuclear levels of ANXA2." (PMID 39273539, 2024).